PGM5P2 (phosphoglucomutase 5 pseudogene 2)
Synonyms: AK096159
Gene: Transcribed unprocessed pseudogene on chromosome 9 (41,039,611 to 41,074,448, reverse strand). Ensembl gene ENSG00000277778.
Diseases named in the same sentence as PGM5P2 in open-access papers:
PGM5P2 is named in the same sentence as 7 diseases in open-access papers, as found by Europe PMC text mining. Sharing a sentence is not in itself a finding about the gene and the disease. The quoted sentences say what the papers report.
lymph node metastasis (1 paper, 2020). "In addition, patients with lymph node metastasis had significantly higher expressions of PGM5P2, HERC2P4 and RRN3P2 but lower expressions of HLA-H and RPL13AP20 than those without lymph node metastasis." (PMID 33378744, 2020).
PGM5P2 also shares sentences with these, for which no sentence is quoted: tumor (2 papers); bone tumor (1); breast carcinoma (1); cancer (1); chordoma (1); prostate tumor (1).